LENEP (lens epithelial protein)
Description:
May play a role in lens epithelial cell differentiation.
Synonyms: LEP503
Tractability: No criterion of Open Targets' tractability assessment is met for any kind of drug.
Gene: Protein-coding gene on chromosome 1 (154,993,586 to 154,994,315, forward strand). Ensembl gene ENSG00000163352.
Gene Ontology:
Molecular function: protein binding; DNA binding
Biological process: lens development in camera-type eye
Genetic constraint (gnomAD): Loss-of-function variants: 4 observed, 5.46 expected, observed/expected ratio (o/e) 0.73, 90% interval 0.36 to 1.6. That is too few expected variants to judge how well the gene tolerates losing a copy. Missense variants: 63 observed, 80.48 expected, observed/expected ratio (o/e) 0.78, 90% interval 0.64 to 0.96. Synonymous variants: 30 observed, 35.58 expected, observed/expected ratio (o/e) 0.84, 90% interval 0.63 to 1.14.
Homologues: Orthologues: chimpanzee LENEP (100% identical), pig LENEP (87% identical), guinea pig LENEP (84% identical), mouse Lenep (80% identical), rabbit LENEP (80% identical), rat Lenep (79% identical), dog LENEP (75% identical), zebrafish lenep (46% identical).